ZEB1 (zinc finger E-box binding homeobox 1)
Diseases named in the same sentence as ZEB1 in open-access papers (continued):
Sharing a sentence is not in itself a finding about the gene and the disease.
glioblastoma (continued). "While we identify a number of EMT-related factors in primary cell lines and tumour specimens, ZEB1 seems to dominate these processes, in up to 50% of patients with glioblastoma." (PMID 23818228, 2013). "Our findings establish ZEB1 as a regulator of invasion and chemoresistance in glioblastoma, and a candidate agent for tumour recurrence." (PMID 23818228, 2013). "ZEB1 is preferentially expressed in invasive glioblastoma cells, where the ZEB1-miR-200 feedback loop interconnects these processes through the downstream effectors ROBO1, c-MYB and MGMT." (PMID 23818228, 2013). "Having established a molecular model for the actions of ZEB1 in glioblastoma, we sought to confirm our studies in specimens of glioblastoma patients." (PMID 23818228, 2013). "Our data indicate that critical stem cell regulators, such as SOX2 and OLIG2, are induced by the ZEB1-miR-200 feedback loop in glioblastoma." (PMID 23818228, 2013). "Here, we provide evidence that the transcription factor ZEB1 (zinc finger E-box binding homeobox 1) exerts simultaneous influence over invasion, chemoresistance and tumourigenesis in glioblastoma." (PMID 23818228, 2013). "Together, these data suggest that invasive cells are capable of evading chemotherapy and support a function of ZEB1 in both glioblastoma invasion and chemoresistance." (PMID 23818228, 2013). "Protein-level analysis shows that about 45% of human glioblastomas express ZEB1, and patients with ZEB1-negative glioblastomas have survival benefits that are likely related to an improved response to TMZ therapy." (PMID 23818228, 2013). "To further corroborate the ZEB1 pathway in glioblastoma invasion and chemoresistance, we performed an immunoblot analysis in glioblastoma samples." (PMID 23818228, 2013). "The activation of the C5a–C5aR1 signaling axis on the glioblastoma cells increases the expression of ZEB1, a regulator of epithelial–mesenchymal transition (EMT), via the p38 MAPK pathway, promoting invasion/infiltration of glioblastoma cells into parenchymal brain tissue." (PMID 38894892, 2024). "In addition, HIF1α had been reported to promote the expression of ZEB1 in hypoxia, and the HIF1α/ZEB1 axis enhanced cancer cells aggressiveness and distant metastasis in bladder cancer and glioblastoma." (PMID 35589690, 2022). "Interestingly, and in line with our observations of the importance of miRNA, EMT, and chemoresistance, a recent report highlights that the miR-200c-ZEB1 feedback loop is involved in the invasion, migration, and chemoresistance in advanced glioblastoma tumors." (PMID 36291907, 2022). "The ZEB1 transcription factor is a known regulator of cellular motility, and it has been shown to be responsible for increased migration of glioblastoma cells and neural stem cells; therefore, it is also a compelling strategy to enhance ZEB1 expression in GRPs." (PMID 34831191, 2021). "Further, we collected experimentally validated genes that could contribute to the invasive ability of glioblastoma cells (such as ZEB1, HNRNPC, WNT5A, and DRAM1) to evaluate the invasive scores for each cell (see section “Materials and Methods”)." (PMID 33505440, 2020). "The glioblastoma database of the Cancer Genome Atlas, (TCGA, n = 539) was used to analyze the correlations between α6-integrin expression and several potential target genes including ZEB1, YAP1, FGFR1, and FOXM1." (PMID 30909436, 2019). "At the forefront of the ZEB1 dichotomy is the role of ZEB1 in glioblastomas." (PMID 30705664, 2018). "Indeed, the study believed that these processes in glioblastoma were intertwined and dependent on ZEB1." (PMID 32309604, 2018).
glioblastoma (continued). "Taken together these data show that ZEB1 may have tumor promoter qualities in glioblastoma and its overexpression leads to poor patient survival as well as increased invasion and metastasis." (PMID 32309604, 2018). "Finally, we show in public gene expression data from bulk glioblastoma samples that ZEB1 inversely correlates with markers of microglia and macrophages." (PMID 28945795, 2017). "In glioblastoma, ZEB1 labeling index is higher in tumors with EGFR amplification or IDH1 mutation." (PMID 28945795, 2017). "Our findings indicated that PTUPB may target the HMMR/SOX2/ZEB1 signaling axis, inhibiting glioblastoma growth." (PMID 29152086, 2017). "The ZEB1 pathway links glioblastoma initiation and invasion." (PMID 25890268, 2015). "We conclude that ZEB1 is a regulator of stemness in glioblastoma." (PMID 23818228, 2013). "Moreover, ZEB1 expression in glioblastoma patients is predictive of shorter survival and poor Temozolomide response." (PMID 23818228, 2013). "To address its functions in invasion we knocked down ZEB1 expression in glioblastoma cells." (PMID 23818228, 2013). "Thus, ZEB1 is an important candidate molecule for glioblastoma recurrence, a marker of invasive tumour cells and a potential therapeutic target, along with its downstream effectors." (PMID 23818228, 2013). "Whether the ZEB1 pathway directly reduces proliferation rates of glioblastoma stem cells remains to be tested." (PMID 23818228, 2013). "Since increased invasion and therapy resistance have been observed in cancer stem cells, and ZEB1 is a known regulator of stemness and SOX2 in other solid tissue cancers, we hypothesised that ZEB1 has similar functions in glioblastoma." (PMID 23818228, 2013). "Our study provides a systematic analysis of the functions of ZEB1 in glioblastoma pathobiology." (PMID 23818228, 2013). "Furthermore, we found that quercetin suppressed GSK-3β/β-catenin/ZEB1 signaling in glioblastoma." (PMID 36386155, 2022). "Finally, the TCGA dataset supports the prognostic value of the ZEB1/miR-200/c-MYB pathway for glioblastoma, as well as significant co-occurrence of ZEB1, MGMT and ROBO1 in these tumours, and decreased levels of EGFR phosphorylation with reduced ZEB1 expression." (PMID 23818228, 2013). "In this context, using glioblastoma models, P2X7 activation has been related to the acquisition of EMT markers in mRNA (CDH2, SNAIL, Zeb1) and proteins (N-cadherin, ZEB1, vimentin, and TWIST), as well as the promotion of spheroid formation." (PMID 37966629, 2025). "Knockdown of MALAT-1 markedly enhanced the sensitivity of multi-resistant glioblastoma cells to Temozolomide (TMZ) by decreasing the expression level of the resistance genes MDR1, MRP5, and LRP1 as well as the mesenchymal markers ZEB1, α-SMA, and fibronectin." (PMID 38201661, 2024). "In glioblastoma, si-MALAT1 downregulated the expression of ZEB1, MDR1, MRP5 and LRP1, enhancing the sensitivity to Temozolomide (TMZ)." (PMID 36829256, 2023). "Thus, ZEB1 might be a target for preventing glioblastoma resistance." (PMID 38139138, 2023). "Because of the link between ZEB1 and SOX2 in glioblastoma, it is worth comparing the functions of both proteins in adult neurogenesis." (PMID 34433050, 2021). "In glioblastoma (GBM) cells, miR-524-5p inhibits ZEB1 to suppress GBM invasion and migration." (PMID 32664703, 2020). "FOXM1 expression in glioblastoma stem like cells has been shown to be elevated via FGFR signaling, wherein the expression of FGFR has been found to be elevated via α6-integrin and ZEB1/YAP1 transcription factor complex." (PMID 33680951, 2020). "Very recently, ZEB1 has been identified as a potential SOX2 target, which is co-expressed with SOX2 in glioblastoma." (PMID 29152086, 2017). "Interrogating the genomes of over 4000 brain cancers we identified ZEB1 deletion in ~15% (grade II and III) and 50% of glioblastomas." (PMID 28246407, 2017).
glioblastoma (continued). "qRT-PCR showed significant upregulation of mesenchymal glioblastoma markers (>100-fold ZEB2; >10-fold TWIST1; FN1, <10-fold VIM; ZEB1; *p < 0.01) in KW10 cells as compared to MTA10 cells." (PMID 28744448, 2017). "In the context of ZEB suppression, binding of ZEB1 to the E-cadherin promoter was dependent on the activation of NF-κB in glioblastoma." (PMID 25197668, 2014). "ZEB1, N-cadherin, ROBO1, MGMT and Engrailed1 are frequently expressed in glioblastoma, confirming our experimental findings." (PMID 23818228, 2013). "Since expression differences are difficult to interpret in immunoperoxidase staining, we performed immunofluorescence imaging for ZEB1, ROBO1 and N-cadherin in glioblastoma specimens." (PMID 23818228, 2013). "Moreover, the single-cell sequencing of bevacizumab-resistant patient glioblastomas confirmed up-regulated mesenchymal genes, particularly glycoprotein YKL-40 and transcription factor ZEB1, in later clones, implicating these changes as treatment-induced." (PMID 38139138, 2023). "The effect of miR-203 (the commonly used name of miR-203a-3p) on ZEB1 and ZEB2 genes was previously shown in many cancer types, such as lung, gastric, cervical, prostate, colon, and renal cancers, as well as glioblastoma, cholangiocarcinoma, and nasopharyngeal carcinoma, for both ZEB1 and ZEB2." (PMID 35163224, 2022). "Next, we removed candidates where publicly available chromatin immunoprecipitation (ChIP) sequencing (ChIP-seq) data in glioblastoma cells indicated no promoter occupancy by ZEB1." (PMID 34433050, 2021). "We recently determined that ZEB1 (Zinc finger homeobox gene), an epithelial to mesenchymal transition (EMT) transcription factor that promotes invasion and metastasis in carcinomas, was deleted in approximately half of glioblastomas." (PMID 30705664, 2018). "ZEB1 is a target of SOX2 and has been shown to be co-expressed with SOX2 in glioblastoma." (PMID 29152086, 2017). "In contrast, our data support findings from a recent study that suggest widespread co-expression of SOX2, OLIG2 and ZEB1 in glioblastoma, irrespective of key driver alterations." (PMID 28945795, 2017). "While not all glioblastomas stained for ZEB1, we found increased expression along the tumour invasion front, in accordance with our findings in xenografts." (PMID 23818228, 2013). "Among other advances, it has been shown that the blocking C-repeat/DRE binding factor 1 (CBF1) in glioblastoma cells can lead to the efficient suppression of epithelial-to-mesenchymal transition (EMT) activators, including zinc finger E-box-binding homeobox 1 (ZEB1)." (PMID 35163235, 2022). "We investigated the effect of miR-200c on ZEB1 expression and cell migration in an in vitro transfection model with a miR-200c mimic, a miR-200c inhibitor and siRNA targeting EGFR in three short-term cultures with different levels of EGFR amplification obtained from resected glioblastomas." (PMID 33396457, 2020). "Additionally, we found that protein expression of ZEB1, but surprisingly not MGMT, correlated with reduced survival of glioblastoma patients, as well as with shorter duration of successful TMZ therapy." (PMID 23818228, 2013). "For example, in glioblastoma (and possibly other tumor types), the glycoprotein Epsin3 (EPN3) may be related to Notch and WNT/β-catenin signaling pathways, and helps to induce EMT in glioblastoma cells after activating SLUG, TWIST, and ZEB1, but not Snail1 or ZEB2." (PMID 33430387, 2021).
bladder cancer (70 papers, 2011 to 2026). "Mechanistically, PFK-1 inhibits histone lactylation of bladder cancer cells, and thus inhibits the transcription activity of ZEB1." (PMID 38481182, 2024). "Our results suggest that PFK-1 can inhibit the malignant phenotype of bladder cancer cells by mediating the lactylation of ZEB1." (PMID 38481182, 2024). "ZEB1 is highly expressed in cancers such as colorectal, pancreatic, oesophageal squamous cell and bladder cancer and contributes to the progression of these tumours." (PMID 38481182, 2024). "In the present study, we found that ZEB1 expression levels were significantly elevated in bladder cancer cells." (PMID 38481182, 2024). "All these results proved that VIM-AS1 facilitated the metastasis ability of both high-metastatic and low-metastatic bladder cancer cells by regulating ZEB1 expression." (PMID 33902589, 2021). "DPYSL2 overexpression also significantly attenuated E-cadherin protein expression, while enhancing Vimentin and ZEB1 protein expression in bladder cancer cells." (PMID 34295887, 2021). "DPYSL2 overexpression significantly attenuated E-cadherin protein expression while enhancing Vimentin and ZEB1 protein expression in bladder cancer cells." (PMID 34295887, 2021). "Next, the predicted interactions between miR-655 and VIM-AS1 and ZEB1 were validated, and functional effects of VIM-AS1, miR-655 and ZEB1 on bladder cancer cell migration and invasion were evaluated." (PMID 33902589, 2021). "Several studies have demonstrated that ZEB1 was significantly overexpressed in bladder cancer tissues compared to normal healthy adjacent tissues." (PMID 31827401, 2019). "Mechanistically, UCA1 regulates bladder cancer cell migration and invasion by miR-145 and its target genes actin-bundling protein fascin and zinc finger E-box binding homeobox 1 and 2 (ZEB1/2)." (PMID 29618386, 2018). "In order to explore the molecular mechanism of ZFAS1 in bladder cancer, we detected the effect of ZFAS1 on the expression of KLF2, NKD2, and EMT-associated genes (ZEB1, E-Cadherin, and Vimentin) by Western blot." (PMID 29678899, 2018). "Western blot analysis of subcellular fraction showed that Snail, Twist-1, and Zeb-1 protein nuclear translocation was inhibited in T24 bladder cancer cells depleted of ILK." (PMID 27683053, 2016). "In bladder cancer, miR-23b inhibited cell proliferation and impaired colony formation by targeting ZEB1 directly." (PMID 27036021, 2016). "In bladder cancer miR-200b and miR-200c have been reported to reduce expression of ZEB1, ZEB2, and ErbB receptor inhibitor-1 and therefore inhibit EMT and restore epidermal growth factor receptor dependency." (PMID 27058893, 2016). "It enhances bladder cancer cell migration and invasion in part though hsa-miR-145/ZEB1/2/FSCN1 pathway." (PMID 27326854, 2016). "Overexpression of SNAI1 and ZEB1 transcripts were detected in all three bladder cancer cell lines stimulated with CAF-CM." (PMID 26152796, 2015). "In a bladder cancer cell line the stable expression of miR-200s increased E-cadherin levels, decreased expression of ZEB-1, ZEB-2, and cell migration, and increased sensitivity to EGFR-blocking agents." (PMID 25058589, 2014). "In conclusion, this study shows that miR-23b has diagnostic/prognostic significance and directly targets oncogenic Zeb1 in bladder cancer." (PMID 23844063, 2013). "A direct correlation between ZEB1 immunoreactivity and Gleason grade has been reported in human prostate tumors and in bladder cancer, ZEB1 has been reported to be over-expressed and responsible for enhanced motility." (PMID 23844063, 2013). "For the first time this study shows that miR-23b is a potential biomarker and tumor suppressor in bladder cancer directly targeting oncogene Zeb1." (PMID 23844063, 2013). "We validated two sets of siRNA (Si-1 and Si-2) that resulted in significant knockdown of Zeb1 at protein level in T24 bladder cancer cells and used one siRNA duplex for further experiments at 50 nM concentration." (PMID 23844063, 2013).
bladder cancer (continued). "We performed Western analysis with miR-23b transfected cells and found that miR-23b attenuated expression of Zeb1 protein compared to cont-miR in both J82 and T24 bladder cancer cells." (PMID 23844063, 2013). "Our data confirm that mesenchymal markers (Zeb-1, Zeb-2, MMPs, and vimentin) are expressed almost exclusively by muscle-invasive tumors, the subset of bladder cancer with worse outcome." (PMID 22253920, 2012). "Additionally, PFK-1 was shown to inhibit histone Kla in bladder cancer cells, thereby reducing the transcriptional activity of ZEB1." (PMID 40484921, 2025). "Of note, miR-205 has been demonstrated to inhibit EMT by repressing ZEB1 in bladder cancer." (PMID 40461454, 2025). "Interestingly, phosphoinositide 3-kinase (PI3K) signaling in bladder cancer promotes bone metastasis by regulating the transcription of Zinc finger E-box-binding homeobox 1 (ZEB1)." (PMID 37666817, 2023). "In addition, UCA1 promotes migration and invasion of bladder cancer cells via the has-miR-145/ZEB1/2/FSCN1 pathway." (PMID 34238213, 2021). "However, the in vivo function of VIM-AS1/miR-655/ZEB1 axis in bladder cancer needs further investigation." (PMID 33902589, 2021). "Conclusively, our findings indicate that circKDM4C may act as a pro-oncogenic factor in BCa invasion and metastasis via the circKDM4C/miR-200bc-3p/ZEB1 axis, which is a potential biomarker or therapeutic target for bladder cancer." (PMID 34811353, 2021). "In conclusion, the VIM-AS1/miR-655/ZEB1 axis might be a promising target for improving bladder cancer metastasis via an EMT-related mechanism." (PMID 33902589, 2021). "﻿In summary, these data indicate that circKDM4C could ﻿function as a sponge for miR-200b-3p/miR-200c-3p to increase ZEB1 expression, which promotes bladder cancer progression eventually." (PMID 34811353, 2021). "The VIM-AS1/miR-655/ZEB1 axis might be a potential target for improving bladder cancer metastasis via an EMT-related mechanism." (PMID 33902589, 2021). "Since VIM-AS1 was predicted by an online tool to target miR-655, herein, we hypothesized that VIM-AS1 might act as a competing endogenous RNA (ceRNA) for miR-655 to offset miR-655-mediated inhibition of ZEB1, therefore modulating bladder cancer cell EMT." (PMID 33902589, 2021). "MiR-429, as other members of miR-200 family, act as a tumor suppressor roles during bladder cancer progression by reducing ZEB1, ZEB2 and restoring E-cadherin which results in downregulation of β-catenin and therefore inhibits cell migratory and invasive ability." (PMID 27058893, 2016). "In bladder cancer cells ZEB1 regulates vimentin, MMP2 and cytokeratins." (PMID 26098771, 2015). "MiR-23b inhibits cell proliferation by post-transcriptionally regulating Zeb1 in bladder cancer." (PMID 25888950, 2015). "Silencing ZEB1 leads to inhibition of bladder cancer cell migration and invasion." (PMID 26098771, 2015). "In NSCLC cells, ZEB1 and Snail were found to be repressors responsible for the regulation of E-cadherin downstream of Cox-2/PGE2, whereas in bladder cancer cells Cox-2 inhibitors downregulated all of the E-cadherin repressors examined: Snail, Slug, Twist, and ZEB1." (PMID 24887090, 2014). "Besides, a recent study has demonstrated that natural flavonoid can suppress bladder cancer metastasis via inhibiting β-catenin/ZEB1 signaling and subsequent EMT." (PMID 24618693, 2014). "In the present study, we found that over-expression of miR-23b resulted in suppression of oncogene Zeb1 in the bladder cancer cells suggesting that miR-23b can mediate EMT, thereby representing a possible mechanism through which it affects bladder cancer migration and invasion." (PMID 23844063, 2013). "Recent work has shown that fibroblast growth factor receptor-1 (FGFR1) promotes invasion of bladder cancer cells expressing ZEB1, a marker of epithelial-mesenchymal transition (EMT); FGFR inhibition in this study reduced metastatic spread of orthotopically implanted bladder cancer cells." (PMID 24312263, 2013).